ZNF793 (zinc finger protein 793)
Description:
May be involved in transcriptional regulation.
Tractability: No criterion of Open Targets' tractability assessment is met for any kind of drug.
Gene: Protein-coding gene on chromosome 19 (37,506,428 to 37,548,762, forward strand). Ensembl gene ENSG00000188227.
Subcellular location: Nucleus
Subcellular location (Human Protein Atlas): Nucleoplasm; Cytosol; Nucleoli
Pathways (Reactome):
Gene expression (Transcription): Generic Transcription Pathway
Gene Ontology:
Molecular function: protein binding; DNA-binding transcription factor activity, RNA polymerase II-specific; RNA polymerase II cis-regulatory region sequence-specific DNA binding
Biological process: regulation of transcription by RNA polymerase II; regulation of DNA-templated transcription
Cellular component: nucleus
Genetic constraint (gnomAD): Loss-of-function variants: 6 observed, 14.64 expected, observed/expected ratio (o/e) 0.41, 90% interval 0.22 to 0.81. The upper end of that interval is the gene's LOEUF score, 0.81, which puts it in group 3 of 6, group 1 being the genes least tolerant of losing a copy. Missense variants: 456 observed, 521.15 expected, observed/expected ratio (o/e) 0.87, 90% interval 0.81 to 0.94. Synonymous variants: 162 observed, 183.06 expected, observed/expected ratio (o/e) 0.88, 90% interval 0.78 to 1.01.
Homologues: Orthologues: chimpanzee ZNF793 (99% identical), macaque ZNF793 (96% identical), guinea pig ZNF793 (86% identical), dog ZNF793 (85% identical), pig ZNF793 (85% identical), rabbit ZNF793 (77% identical), tropical clawed frog zfx (16% identical), mouse Zfy1 (16% identical), rat Zfy1 (16% identical), zebrafish zfx (16% identical), mouse Zfy2 (15% identical). Paralogues in human: ZSCAN20 (37% identical), ZNF551 (33% identical), ZSCAN2 (33% identical), ZNF583 (32% identical), ZNF792 (32% identical), ZNF256 (31% identical), ZNF480 (31% identical), ZNF570 (30% identical), ZNF304 (30% identical), ZNF549 (30% identical), ZNF773 (30% identical), ZNF79 (29% identical), and 26 more.
Diseases named in the same sentence as ZNF793 in open-access papers:
ZNF793 is named in the same sentence as 7 diseases in open-access papers, as found by Europe PMC text mining. Sharing a sentence is not in itself a finding about the gene and the disease. The quoted sentences say what the papers report.
gastric cancer (2 papers, 2021 to 2025). A primary or metastatic malignant neoplasm involving the stomach. "Herein, we provided molecular clues to further investigate the practical utilities of the quantification of RPRM and ZNF793 DNA methylation level as a marker for gastric cancer risk." (PMID 34199386, 2021). "Our results, by demonstrating the epigenetic-associated silencing of cancer-related genes (ZNF793 and RPRM), provide a molecular mechanism to explain the increased risk of IM progressing to the intestinal type of gastric cancer." (PMID 34199386, 2021). "Although genome-wide promoter CpG island hypermethylation of Epstein–Barr virus-associated gastric carcinoma (EBV GC) is well known, ZNF793 is rarely methylated in EBV GC but is frequently methylated in other molecular subtypes of GC, including microsatellite instability-high GC." (PMID 40545504, 2025). "We identified CpG methylation at the ZNF793 and RPRM promoters as a common event in intestinal metaplasia and intestinal forms of gastric cancer." (PMID 34199386, 2021). "We also analyzed the methylation level of ZNF793 and RPRM genes in a set of gastric cancer cell lines (n = 31) from which we had in-house methylation data (freely available at GEO: GSE68379)." (PMID 34199386, 2021). "A gain of methylation was observed for ZNF793 and RPRM genes in the intestinal type of gastric cancer compared with their normal paired counterpart (p < 0.005)." (PMID 34199386, 2021).
esophageal adenocarcinoma (1 paper, 2021). A malignant tumor with glandular differentiation arising predominantly from Barrett mucosa in the lower third of the esophagus. "The ZNF793 gene is especially enticing because methylation of its promoter has been previously proposed as a detection biomarker for Barret’s esophagus, a premalignant condition for esophageal adenocarcinoma." (PMID 34199386, 2021).
cancer (3 papers, 2021 to 2025). A tumor composed of atypical neoplastic, often pleomorphic cells that invade other tissues. "In absolute numbers, we obtained ZNF793 methylation data for 9 patients and RPRM methylation data for 5 patients with cancer progression." (PMID 34199386, 2021). "Two epigenetically regulated genes in cancer, RPRM and ZNF793, consistently showed increased methylation in intestinal metaplasia with respect to earlier precursor lesions." (PMID 34199386, 2021). "Methylation at the ZNF793 and RPRM genes is initiated during IM, and reaches the highest levels in cancer samples." (PMID 34199386, 2021). "The ability of ZNF793 to evade methylation in EBV GC, but not in other GC subtypes, highlights its potential role in this cancer type." (PMID 40545504, 2025).
tumor (1 paper, 2025). "The present study, for the first time, characterized the biological processes associated with ZNF793, including tumor stemness, cell proliferation, migration, invasion, and inhibition of apoptosis." (PMID 40545504, 2025). "When ZNF793 was reintroduced into the knockout cells, the number of tumor spheres increased." (PMID 40545504, 2025). "Similarly, ZNF793 knockdown in SNU620 cells resulted in decreased tumor sphere formation." (PMID 40545504, 2025). "Additionally, ZNF793 knockout significantly inhibited tumor growth in a xenograft tumor model." (PMID 40545504, 2025). "ZNF793 expression was knocked out and then restored in EBV and non-EBV GC cell lines, and its effects on cell proliferation, cell migration, cell invasion, tumor sphere formation, and xenograft tumor formation were assessed." (PMID 40545504, 2025). "In the xenograft tumor assay, engraftment of both SNU719 and AGS cells with ZNF793 knockout resulted in a significant decrease in tumor volume, and restoration of ZNF793 expression resulted in restoration of tumor volume." (PMID 40545504, 2025). "The common role of ZNF793 and MLH1 in EBV GC is tumor stemness, so it is presumed that the main reason why DNA methylation of MLH1 and ZNF793 is not observed in EBV GC is attributed to tumor stemness." (PMID 40545504, 2025).
ZNF793 also shares sentences with these, for which no sentence is quoted: dengue (1 paper); diabetes (1); endometrial carcinoma (1).